IL6 (interleukin 6)
Diseases named in the same sentence as IL6 in open-access papers (continued):
Sharing a sentence is not in itself a finding about the gene and the disease.
diabetes (continued). "Animal study and human studies have found that diabetes could accelerate the appearance of cerebrovascular inflammation and Aβ deposition, as evidenced by increased levels of proinflammatory cytokines such as interleukin (IL-6) and tumor necrosis factor (TNF-α)." (PMID 31296192, 2019). "Univariate analysis showed that age, MetS, INS, Lg(hs-CRP), Lg(IL-6), FFAs, Lg(APN), SBP, DBP, body mass index (BMI), smoking, diabetes, family history of hypertension, and dyslipidemia were differed significantly between CVD and non-CVD cases." (PMID 31191115, 2019). "In the present study, induction of diabetes increased (p < 0.05) levels of proinflammatory cytokines TNF-a, IL-1b and IL-6 in rats." (PMID 31412679, 2019). "This study was aimed to investigate the effect of golden sea cucumber extract on PC, IL-6, and Glut-4 level of STZ-induced diabetes mouse." (PMID 31327904, 2019). "The 68 studies that examined diabetes/inflammation measures (HOMA-IR, insulin, glucose, C reactive protein, interleukin-6, alanine transaminase and the 71 studies examining cardiac measures (eg, lipids, cholesterol, blood pressure) will be reported separately." (PMID 31473614, 2019). "Many studies have shown that proinflammatory cytokines including TNF-α, IL-6, IL-1β, CRP, and NF-κB can lead to IR and the development of related diseases such as metabolic syndrome and diabetes, either alone or in combination, via various pathways." (PMID 31218568, 2019). "As compared with controls and after adjustment for age, sex and diabetes mellitus, sVCAM-1, E-selectin, thrombomodulin, hs-CRP, SAA, IL-6, and TNF-α were higher in CKD5-ND, CKD5-HD and CKD5-PD." (PMID 31518378, 2019). "TNF-α, IL-6, and MMP-9 were significantly upregulated in traumatized skin of rats with STZ-diabetes than in normal trauma rats (NC group) (p < 0.05)." (PMID 31605256, 2019). "Weobserved a statistically significant decrease of MCP-1/CCL2, GM-CSF, IL-5,IL-6, and IFN-γ in the saliva of patients with chronic periodontitisassociated with type 2 diabetes mellitus in comparison with patients withchronic periodontitis only." (PMID 31993238, 2019). "Thus, our study corroborates the notion that IL-6 may not be associated with depressive symptoms in patients with diabetes and that diabetes may have an effect-modifying impact on the association seen in the general population." (PMID 29520075, 2018). "The immune response to the proinsulin-2 peptides escalated from a mild Th1/Th17 response 1 week post prime to an abundant production of IFN-γ, IL-6 and TNF-α in particular by week 7, the time of earliest diabetes onset." (PMID 30237494, 2018). "Exercise induced a decrease in the pro-inflammatory cytokines, such as tumor necrosis factor α (TNF-α) and IL-6, C-reactive protein (CRP), thereby assisting the prevention or mitigation of such chronic-degenerative diseases such as obesity and diabetes." (PMID 30666216, 2018). "Increased levels of cytokines, including IL-1β, IL-6, IL-8, VEGF and TNFα have been found in diabetic patients and rodent models of diabetes." (PMID 29301251, 2018). "The levels of cytokines (e.g., IL-6, IL-1β, IL-10, and IL-12) and chemokines (e.g., MCP-1, MIG, and RANTES) are perturbed in MDMs derived from patients with diabetes, both before infection and in response to Mtb infection." (PMID 29513874, 2018). "In diabetics, the systemic levels of LTB4, TNF-α, IL-6, IL-10, IL-12 and IFNγ were increased as well as the frequency of pro-inflammatory monocytes (CD11b+Ly6ChighLy6G−) compared to healthy mice." (PMID 30242286, 2018). "In previous studies, cataract surgery may induce the elevation of vascular endothelial growth factor, monocyte chemotactic protein-1, interleukin-1β (IL-1β), and IL-6 in the aqueous fluid of patients with and without diabetes by causing changes to the blood–retinal barrier." (PMID 30133506, 2018).
diabetes (continued). "Early inflammatory events in diabetes triggers the release of pro-inflammatory cytokines including TNF-α, IL-1β, and IL-6, which gradually increase as the disease progresses." (PMID 30443223, 2018). "The current study shows that Lf decreased diabetes-induced inflammation by inhibiting the TLR-4-NF-κB axis with subsequent reduction in serum proinflammatory cytokines; IL-1β, IL-6, and IL-18, in diabetic children." (PMID 30534206, 2018). "Compared with NC, the levels of serum inflammation indexes like CRP, IL6, IL8, TNF-α, and CCL2 were significantly increased (p < 0.05), while IL10 levels were significantly decreased (p < 0.05) in diabetes groups (MC, WP and SCCOPs-treated groups)." (PMID 29316680, 2018). "Results exhibited that higher mRNA levels of CRP, IL-6, IL-1β, and TNF-α in diabetes rats were obviously reduced after the treatment with STX for 7 weeks." (PMID 30210342, 2018). "Prior studies of inflammation-related markers and diabetes have measured a limited number of inflammatory markers, primarily C-reactive protein (CRP) and interleukin 6 (IL-6) and, more recently, anti-inflammatory cytokines." (PMID 28753646, 2017). "It was previously reported that inflammatory responses such as IL-6 and TNF-α accumulated oxidative damage products in the liver of diabetes mellitus (DM) patients." (PMID 28811499, 2017). "In line with previous findings, NOD macrophages produced higher protein levels of IL-6 and CXCL-1 (KC) and an upward tendency for TNFα and MCP-1, compared to non-diabetes-prone control C57BL/6 counterparts." (PMID 29095944, 2017). "We also found that both diabetes and genetic variations of FTO, IL-6, HSPD1 genes were equally distributed across clinical characteristics of breast cancer." (PMID 28591216, 2017). "To further investigate the role of TIPE2 in diabetes, we studied the relationship between TIPE2 mRNA expression and the serum concentrations of hsCRP, TNF-α, and IL-6." (PMID 28626770, 2017). "In the current study, IL-6 was increased in the serum and kidney tissue in positive group as a result of STZ-induced diabetes." (PMID 28298934, 2017). "In guinea pigs, pro-inflammatory cytokines such as tumor necrosis factor (TNF)-alpha and interleukin 6 (IL-6) produced during inflammation promote the release of free fatty acids from adipose tissue which may reduce insulin action on skeletal muscles resulting in dysglycaemia and diabetes mellitus." (PMID 28137307, 2017). "We also found that TonEBP+/− mice had reduced levels of hepatic lipogenic factors, HMGB1, IL-6, and TNF-α expression, as well as reduced macrophage infiltration and proinflammatory cytokines in adipose tissues of HFD/STZ-induced diabetes." (PMID 28798347, 2017). "Before treatment with melatonin, levels of IL-1β, IL-6 and PGE2 in gingival crevicular fluid of patients with diabetes and perio-dontal disease were significantly higher than in healthy control subjects without periodontitis." (PMID 29075409, 2017). "The diabetes + IR group had significantly (p < 0.001) high levels of TNF-α and IL-6 as compared to the diabetic-control group." (PMID 28505121, 2017). "Observed results about prevention of experimental streptozotocin-diabetes only in DP pretreated groups, may suggest that purine compounds, uric acid and some volatile toxic compounds may suppress oral tolerance, probably via IL-6 and TGF-β cytokine interaction." (PMID 28176796, 2017). "Inflammatory mediators such as TNF-α, IL-6, and CRP, which are elevated in COPD, are also increased in diabetes." (PMID 27335596, 2016). "Patients with diabetes have increased circulating levels of inflammatory markers including tumor necrosis factor-α (TNF-α), interleukin-6 (IL-6), and chemokine (C–C motif) ligand 2 (CCL2)." (PMID 26861446, 2016). "SASP genes (i.e., IL-1α, IL-1β, IL-6, and TNF-α) are chronically activated in cells and tissues from diabetes patients." (PMID 27340505, 2016).
diabetes (continued). "Our experiments showed that the presence of diabetes led to elevated expression of TNF-α, IL-6 and p-NFκB in tumor tissues." (PMID 27413117, 2016). "Western blotting analysis demonstrated a significant increase in the amount of immunoreactive peptide corresponding to gene expression of IL-1β, IL-6, and TGF-β1 in renal tissue from group with diabetes compared to the control group (resp)." (PMID 26955430, 2016). "As expected, CKD 5 patients had a higher burden of comorbidities, including diabetes mellitus, CVD and PEW, lower mGFR, plasma albumin and hemoglobin levels and higher levels of creatinine, hsCRP and IL-6, compared with CKD 3–4 patients and controls." (PMID 26751065, 2016). "Diabetes-induced p38 MAPK activation promotes the production of inflammatory factors, including TNF-α, IL-1, IL-4, IL-6 and IL-8, by tissues and cells." (PMID 27413117, 2016). "In the current study, interleukin-6 levels were increased in the serum and kidney tissue homogenate as a result of diabetes in G2 as a result of STZ induced diabetes." (PMID 27525022, 2016). "Together, these results are important because PGE2 production is elevated in inflammatory states, including in some cases diabetes, and PGE2-EP4 has been shown to mediate detrimental effects on the kidney in diabetic mice through increased IL-6 production." (PMID 27351842, 2016). "Western blot results showed that diabetes resulted in significantly elevated TNF-α, IL-6 and p-NFκB expression in primary and metastatic tumors, while SB203580 treatment markedly reduced their expression." (PMID 27413117, 2016). "In this study, we have shown that diabetes enhances the increase in HMGB1 serum levels and expression of the inflammatory cytokines IL-1β, IL-6, and inflammation-related enzyme after cerebral I/R injury in mice." (PMID 27596007, 2016). "Consistently, the stimulatory effect of diabetes on peritoneal macrophage Il6 was mediated by PGE2-EP4, while PGE2-EP4 suppressed the effect of diabetes on Tnfa in these cells." (PMID 27351842, 2016). "This fact, coupled with the collinear increase in age, diabetes, AS and the CHA2DS2-VASc score, prevented us from adjusting our models by IL-6 values." (PMID 27568019, 2016). "Studies in human diabetic individuals revealed that hyperglycaemia acutely increases circulating cytokine concentrations of IL-6 and TNF-α by an oxidative mechanism, and plays a role in immune activation in diabetes." (PMID 25923079, 2015). "Serum and urinary levels of IL-6 and IL-18 were significantly elevated, but those of TTP were significantly decreased in patients with diabetes as compared with control subjects." (PMID 26517838, 2015). "Chronic inflammation occurred in the diabetic pancreas accompanied by up-regulation of CCAAT/enhancer-binding protein beta (C/EBPβ) and its targets (TNFα, Il6, CRP, and Fn1) as well as myeloperoxidase (Mpo) and C-X-C chemokine receptor type 2 (Cxcr2)." (PMID 26110898, 2015). "This contrasts with previous findings in C57Bl/6 mice at later time points after 8 weeks of diabetes, in which we were able to detect increased ICAM-1 mRNA in retinal vessels and enhanced levels of TNFα, IL-6, and IL-1β mRNA in whole-retina homogenates." (PMID 25918731, 2015). "Patients with diabetes and periodontal disease had significantly higher mean levels of serum TNF-α, IL-6 and CRP than healthy subjects (P < 0.001)." (PMID 26644840, 2015). "Patients with diabetes and periodontal disease had significantly higher mean levels of serum TNF-α (1.79 ± 0.19 vs 0.82 ± 0.17 pg/mL), IL-6 (0.57 ± 0.07 vs 0.38 ± 0.05 pg/mL), and CRP (0.39 ± 0.11 vs 0.21 ± 0.08 mg/L) by comparison with healthy subjects." (PMID 26644840, 2015). "PATs from SENP1-aP2KO mice expressed high levels of IL-6, TNF-α and IL-1β at the age of 7 weeks before the onset of diabetes, and these proinflammatory cytokines were higher in the PATs compared with other adipose depots." (PMID 26596471, 2015).
diabetes (continued). "Finally, IL-6 and IL-8 can induce white blood cell production and it has been speculated that increased cytokines are responsible for heightened cell counts in cardiovascular disease and diabetes." (PMID 26378783, 2015). "Local melatonin application in patients with diabetes and periodontal disease resulted in a significant decrease in CRP and IL-6 serum levels as well as an improvement in the gingival index and pocket depth." (PMID 26644840, 2015). "Urinary and serum levels of IL-6 and IL-18 mRNA were significantly elevated but those of TTP were significantly decreased in diabetes patients compared with healthy controls (P<0.001)." (PMID 26517838, 2015). "There is a significant elevation in the interleukin-6 (IL-6), C-reactive protein (CRP), tumour necrosis factor-alpha (TNF-α) and IL-1β levels in preclinical diabetes samples." (PMID 26596471, 2015). "Circulating IL-6 and TNF-α were markedly different among these groups with a tendency of increment in accordance with the emergence of diabetes and diabetic microangiopathy (P < 0.05 or P < 0.01)." (PMID 26106251, 2015). "The BMI/WHtR 5-category variable was a significantly better discriminator of high triglycerides, low HDL-C, pre-diabetes, high C3, CRP, IL-6, TNF-α and WBC levels compared to BMI, and of leptin compared to WHtR." (PMID 26351521, 2015). "At long times post-PHx, NASH was characterized by sustained high levels of GF signaling, ASH was characterized by sustained high levels of IL-6 and reduced ECM accumulation, and diabetes was characterized by reduced ECM accumulation." (PMID 26493454, 2015). "All evaluated comorbidities were related to higher IL-6; FDs in IL-6 were 1.08 [1.04-1.12] for smoking, 1.12 [1.02-1.24] for CVD, 1.07 [1.00-1.16] for diabetes and 1.12 [1.02-1.24] for HBV (1.15 [1.02-1.30]) and 1.53 [1.45-1.62] for HCV." (PMID 25393991, 2014). "CRC initiation and promotion by diabetes is due to diabetes-induced increase in growth factors (e.g., insulin, IGF-1) and inflammatory adipo/cytokines (e.g., TNFα, IL-6)." (PMID 25375205, 2014). "The aim of this study was to investigate the effect of APS on adiponectin and IL-6 secretion by 3T3-L1 cells, and to evaluate the potential of APS for clinical diabetes treatment." (PMID 24926351, 2014). "Several studies have shown high levels of interleukin-6 (IL-6) and TNF-α among individuals with clinically diagnosed diabetes." (PMID 25551102, 2014). "The enhanced pro-inflammatory burden in diabetic mice is also reflected by the overall increased levels of circulating plasma cytokines (IL-6, IFN-γ, IL-12p70, IL-1β, IL-10, TNFα, OPN and sVCAM-1) after 8 weeks of diabetes." (PMID 23755169, 2014). "COPD patients exhibit elevated levels of inflammatory biomarkers including CRP, TNF-α, fibrinogen, leukocytes, IL-6, and IL-8 suggesting that COPD may be similar to other diseases associated with systemic inflammation including CAD, peripheral arterial disease, osteoporosis and diabetes." (PMID 25480156, 2014). "Puerarin at 20 and 100 nM decreased the diabetes-induced elevation of TNF-α, IL-1β, and IL-6 (P < 0.001) and NF-κB DNA binding activities (P < 0.01 and P < 0.001 at 20 nM and 100 nM, resp.)." (PMID 25089076, 2014). "It is known that diabetes induces the expression of various cytokines, such as TNF-α and IL-6, by immune cells." (PMID 24000330, 2013). "After 12 weeks of diabetes, renal protein and mRNA MCP-1 and ICAM-1 expression, and levels of TNF-α and IL-6, were markedly increased in the DM group, as compared with NC rats." (PMID 23935673, 2013). "A number of proinflammatory cytokines/chemokines including TNF-α, IL-1 and IL-6, and MCP-1 were well documented to involve in the pathogenesis of diabetes mellitus." (PMID 24078930, 2013). "Intravitreal administration of the ERK1/2 inhibitor U0126 prior to induction of diabetes decreased ERK1/2 activation, attenuated diabetes-induced upregulation of MMP-9, iNOS, IL-6, and TNF-α and upregulated TIMP-1 expression." (PMID 23671886, 2013).
diabetes (continued). "In this study, ssEFV and CAC were associated, and this finding remained robust in the multi-variable regression Model 1 adjusted for abdominal obesity, albuminuria, renal function, diabetes mellitus, HDL cholesterol, and IL-6." (PMID 23351146, 2013). "Post-prandial inflammation is characterized by an increase in IL-6 and TNF-α in both normal individuals and those with diabetes." (PMID 23844276, 2013). "Cytokines involved in psoriasis, PsA, and diabetes include tumor necrosis factor-alpha (TNF-α), IL-1, and IL-6." (PMID 23843781, 2013). "Increased levels of pro-inflammatory cytokines MCP-1, IL-1β, IL-6, IL-18 and TNF-α have been reported in diabetes." (PMID 24359406, 2013). "In the diabetic mice, we observed aberrant and significantly elevated levels of IL-1α, IL-1β, IL-6 and CXCL10 compared to the control group, which indicated prolonged proinflammatory conditions during diabetes." (PMID 23533683, 2013). "In our current study, IMD administration decreased diabetes-induced myocardial NF-κB activation, cytochrome C oxidase expression, and serum/myocardial TNF-α, IL-1, and IL-6 expression." (PMID 23777472, 2013). "Since elevated IL-1β, IL-6, and TNF-α were referred to as independent predictors of diabetes, decreased concentrations reveal the antidiabetic properties of functional food." (PMID 23690866, 2013). "Although the possible relevance of cytokines such as Il-6 and TNF-α to ADT-related diabetes has been suggested, its mechanism is poorly understood." (PMID 22792092, 2012). "TNF-α, IL-6, MCP-1 and CRP are elevated in obese individuals, and predict diabetes and cardiovascular disease." (PMID 22984471, 2012). "Relevance of elevated serum IL-6, and TNF-α levels to insulin resistance and diabetes has been shown accordingly." (PMID 22792092, 2012). "Immunohistochemical procedures for MMP-2, MMP-9, TNF-α, IL-1β, IL-6, RANKL, and RAGE were performed in rats after 1, 3, 6, 9, and 12 months of diabetes induction." (PMID 22611374, 2012). "In the Sandy Lake Health and Diabetes Project, leptin, CRP, IL-6 and serum amyloid A were included in a risk model based on cardiometabolic risk factors, adiponectin and impaired glucose tolerance, but could not improve diabetes prediction." (PMID 21674000, 2011). "it was demonstrated that diabetes increased proinflammatory cytokines including TNF-α, IL-1β and IL-6 in the circulating, renal production, and urinary excretion." (PMID 21699681, 2011). "In this study, we demonstrated that male TH mice as a polygenic diabetes model developed an osteoporotic phenotype with decreased bone density and increased osteoclastogenic factors, such as IFN-γ, IL-6, and RANKL, in the blood and bone marrow." (PMID 21464945, 2011). "Vitamin E supplementation in patients with diabetes decreases the levels of proinflammatory cytokines, such as IL-1, TNF-α, IL-6, and reactive C protein, in serum and stimulated monocytes." (PMID 21352586, 2011). "TSN decreased the levels of IL-6 (20.3 ± 5.5 vs 26.5 ± 6.3 pg/mg protein, P < 0.05) and TNF-α (69.0 ± 12.4 vs 89.7 ± 10.2 pg/mg protein, P < 0.05) compared with the diabetes group." (PMID 21232147, 2011). "The associations, however, still remained significant except for IL-6.Further adjustment for alcohol intake, smoking, GFR, diabetes, hypertension and useof diuretics, had little impact on the associations." (PMID 21625475, 2011). "The proinflammatory cytokines TNF-α and IL-6 have been shown to both suppress and antagonize the action of APN in diabetes." (PMID 21912612, 2011). "And we did not consider patients who underwent surgery or those who had any concomitant disease suspected of raising VEGF, IL-6, or CRP (i.e., chronic inflammatory disorders, diabetes mellitus, ischemic heart disease, etc.)." (PMID 20465852, 2010). "Several well-known markers of inflammation secreted by the adipose tissue, including IL-6 (which stimulated the hepatic synthesis of CRP), IL-1β and TNF-α, have been referred as independent predictors of diabetes." (PMID 20652060, 2010).